GABRA4 (gamma-aminobutyric acid type A receptor subunit alpha4)
Diseases named in the same sentence as GABRA4 in open-access papers:
GABRA4 is named in the same sentence as 42 diseases in open-access papers, as found by Europe PMC text mining. Sharing a sentence is not in itself a finding about the gene and the disease. The quoted sentences say what the papers report.
autism (9 papers, 2012 to 2023). Persistent deficits in social interaction and communication and interaction as well as a markedly restricted repertoire of activity and interest as well as repetitive patterns of behavior. "GABRA4 was also found to increase autism risk through interaction with GABRB1, indicating a complex gene–gene interaction in GABA receptor subunit genes involved in the ethology of autism." (PMID 35198562, 2021). "Moreover, GABRA4 KO mice show an autistic-like behaviour, and autism has been associated with an increased number of spines." (PMID 37684532, 2023). "Our results suggest that GABRA4 deficiency may contribute to the etiology of autism, confirming causality of GABRA4 variations identified in the previous studies on ASD patients." (PMID 32033586, 2020). "The GABRA4 gene was reported to be associated with autism in multiple ethnic groups." (PMID 32033586, 2020). "Here, in order to establish mutant GABRA4 as a causal gene in autism and search for underlying mechanisms, we generated Gabra4 knockout mice (Gabra4−/−) which showed core features of autism, enhanced spatial memory, and attenuated susceptibility to pentylenetetrazol-induced seizures." (PMID 32033586, 2020). "It was reported that the GABA (A) receptor 4 gene (Gabra4) could contribute to autism susceptibility in humans." (PMID 22291890, 2012). "Previous studies on Gabra4 knockout mice demonstrated the involvement of the Gabra4 subunit in synaptic plasticity and spatial learning during puberty, and in contextual fear memory, but did not report any autistic-like behaviors, probably due to the ignorance of its association with human autism." (PMID 32033586, 2020). "As GABRB1 and GABRA4 lie within the same GABAR gene cluster and their promoters are head-to-head, it is interesting to note that the association of GABRA4 with autism risk increases with a GABRB1 interaction, suggesting that these genes may be coordinately regulated." (PMID 30186109, 2018). "Association studies also suggest that GABRA4 and GABRB1 contribute to the susceptibility for autism." (PMID 32033586, 2020). "The enrichment of human ASD and epilepsy candidate genes and LM-related genes in the hippocampal differentially expressed genes further confirms the Gabra4−/− mouse as a potential animal model for a subtype of autism at molecular level." (PMID 32033586, 2020). "These phenotypes of Gabra4−/− mice show HF-autism-like features: impaired social interaction and repetitive behaviors, no intellectual disability (even better than normal in spatial learning and memory) and attenuated susceptibility to seizure." (PMID 32033586, 2020). "To further search for converged pathways involved in autistic-like behaviors, abnormal learning/memory and anti-epilepsy phenotypes of Gabra4 knockout mice, we mapped autism candidate genes onto the hippocampal interactome and extracted ASD subnetwork, EP subnetwork, and LM subnetwork." (PMID 32033586, 2020). "A family-based association and linkage disequilibrium study has found a genetic interaction between GABRA4 and GABRB1 in the etiology of autism." (PMID 32033586, 2020). "However, these previous Gabra4 knockout mice were not evaluated for the autistic phenotypes, including the core features of autism such as impaired social interaction, stereotyped behaviors, or restricted interests." (PMID 32033586, 2020).
epilepsy (9 papers, 2010 to 2024). A brain disorder characterized by episodes of abnormally increased neuronal discharge resulting in transient episodes of sensory or motor neurological dysfunction, or psychic dysfunction. "Previously, we reported one patient with epilepsy with a de novo missense variant in GABRA4, thus making this a candidate gene for monogenic epilepsy." (PMID 38565639, 2024). "Previously, we reported the de novo variant p.(Thr300Ile) in GABRA4 in a patient with epilepsy and neurodevelopmental abnormalities." (PMID 38565639, 2024). "A comprehensive functional characterization of the detected variant demonstrates a molecular change‐of‐function, thus providing first evidence for an association between variants in GABRA4 and a neurodevelopmental disorder with epilepsy." (PMID 35152403, 2022). "In conclusion, our findings strongly suggest an association between de novo variation in GABRA4 and a neurodevelopmental disorder with epilepsy." (PMID 35152403, 2022). "Here, we report a novel de novo missense variant in GABRA4 in an individual with early‐onset epilepsy and various neurodevelopmental abnormalities." (PMID 35152403, 2022). "In summary, our findings represent the first genetic and functional evidence for an association between GABRA4 and a neurodevelopmental disorder with epilepsy." (PMID 35152403, 2022). "Here, we report a de novo missense variant in GABRA4 (c.899C>T, p.Thr300Ile) in an individual with early‐onset drug‐resistant epilepsy and neurodevelopmental abnormalities." (PMID 35152403, 2022). "ASDs are frequently comorbid with epilepsy and thus we tested the impact of the Gabra4 knockout on susceptibility to the seizure-inducing drug pentylenetetrazol (PTZ)." (PMID 32033586, 2020). "Provided that future replications will reinforce a causal relationship, GABRA4 may soon be added to the constantly growing list of epilepsy‐related disease genes." (PMID 35152403, 2022). "Five drugs met these criteria: Topiramate in ATC N03AX (treating epilepsy, targeting GABRA4), Desipramine, Imipramine, and Nortriptyline in ATC N06AA (treating depression and anxiety, targeting BDNF) and Methylphenidate in ATC N06BA (treating ADHD, targeting DRD2)." (PMID 39070649, 2024). "Taken together, converging evidence suggests GABRA4 as a candidate gene for epilepsy." (PMID 35152403, 2022). "Hence, similar findings need to be replicated in additional patients to corroborate GABRA4 as a monogenic epilepsy gene." (PMID 35152403, 2022). "While Gabra4 knockout mice do not exhibit overt seizures, they are more susceptible to pentylenetetrazole induced seizures, and transcription profiling has shown alterations in the expression of genes involved in epilepsy, autism, and memory." (PMID 38565639, 2024). "For example, GABRA4 was upregulated 606-fold in ASD LCLs and regulated pathways of epilepsy and neurodevelopmental disorders." (PMID 35743705, 2022). "In developing neurons and epilepsy, BDNF is the endogenous signal that induces EGR3 expression via a PKC/MAPK-dependent pathway, and then EGR3 up-regulates the expression of GABRA4 by binding its promoter." (PMID 20156358, 2010). "Although GABRA4 has not been established as a monogenic epilepsy gene thus far, GABAA receptor–encoding genes in general are among the best‐studied genetic risk factors contributing to epilepsies." (PMID 35152403, 2022). "We found that variants in the epilepsy-associated genes GABRA1, GABRB3 and GABRG2 were mainly present in the ESP variants, but the GEC cohort contained epilepsy-associated GABRA6, GABRB1, and GABRB2 and non-epilepsy- associated GABRA4, GABRA5, and GABRG3 genes." (PMID 27622563, 2016).
Anxiety (5 papers, 2013 to 2024). Intense feelings of nervousness, tension, or panic often arise in response to interpersonal stresses. "Amygdalar genes that were changed across treatment groups also were related to psychological conditions such as depression (Drd2), stress enhanced fear learning (Gabra4), chronic mild stress (Drd1a), and anxiety, mood disorders, and psychoses (Htr3a)." (PMID 25165739, 2014).
alcohol dependence (2 papers, 2015 to 2021). Physical and psychological dependence on alcohol. "In support of Gabra2-Gabrb1 covariance in expression, a GABRA2 risk variant for alcohol dependence leading to reduced expression of GABRA2 positively correlated with expression of GABRB1, GABRG1 and GABRA4 in human iPSCs." (PMID 34677900, 2021). "The downregulation of Gabra4 expression upon AW temporally correlated with the upregulation of a cohort of miRNAs that have been proposed in many studies to have physiological significance related to seizure, stress, alcoholism, epigenetics, immunity, and synaptic functions." (PMID 26357588, 2015).
autism spectrum disorder (2 papers, 2020 to 2025). A spectrum of developmental disorders that includes autism, and Asperger syndrome. "Mutations in GABRA4 are associated with autism spectrum disorders (ASDs)." (PMID 41035938, 2025).
nicotine addiction (2 papers, 2018 to 2023). "The amino acid substitution caused by the GABRA4 polymorphism rs2229940 is predicted as deleterious by using SIFT and as benign by using PolyPhen, and it was reported to display a marginal association with nicotine dependence." (PMID 29445327, 2018).
schizophrenia (2 papers, 2017 to 2022). A major psychotic disorder characterized by abnormalities in the perception or expression of reality. "Both GABRA4 and GABRB1 mRNA and protein were found to alter their expression in the parietal and frontal cortex and cerebellum of patients with ASD and in the lateral cerebellum of patients with schizophrenia and with affective disorders." (PMID 29179725, 2017).
alcohol addiction (1 paper, 2015). "These in vitro data will help to drive future studies using an in vivo model of AW to better understand the role of these miRNAs in alcohol addiction and their effects on Gabra4 expression and inhibition in the brain." (PMID 26357588, 2015).
anorexia nervosa (1 paper, 2021). A disorder most often seen in adolescent females characterized by a refusal to maintain a minimally normal body weight, an intense fear of gaining weight, a disturbance in body image, and, in postmenarcheal females, the development of amenorrhea. "However, it is known that the 4α- subunit exhibits high plasticity and in the anx/anx mouse model of anorexia nervosa, there is a ~3-fold up-regulation in Gabra4 in the hypothalamus." (PMID 33925570, 2021).
cocaine addicts (1 paper, 2013). "Factor 3: chr 4 gene cluster: with the exception of GABRA4 that loads more strongly on factor 1, the other three chr 4 complex genes had altered expression in alcoholics/cocaine addicts." (PMID 23717525, 2013).
developmental delay (1 paper, 2024). "In addition to these genes, GABRA4, encoding the α4-subunit of the GABAAR, has recently been posited as a candidate gene based on our previous work in which we identified the p.(Thr300Ile) de novo missense variant in a patient with early-onset intractable epilepsy and developmental delay." (PMID 38565639, 2024).
dilated cardiomyopathy (1 paper, 2022). Cardiomyopathy which is characterized by dilation and contractile dysfunction of the left and right ventricles. "Second, AQP4, VSNL1, GABRA4, and GABRB1 were still among the hub genes obtained by subgroup analysis, indicating that these genes were strongly associated with dilated cardiomyopathy caused by myocarditis." (PMID 36286305, 2022).
focal epilepsy (1 paper, 2022). A seizure caused by a localized disorder. "Here, we report an individual with early‐onset focal epilepsy and neurodevelopmental abnormalities, in whom we identified a de novo missense variant in GABRA4 (c.899C>T, p.Thr300Ile) using trio ES." (PMID 35152403, 2022).
neuroblastoma (1 paper, 2023). Neuroblastoma (NB) is the most common solid, extracranial childhood tumor. "In neuroblastoma cells, Gabra4 expression is controlled by the transcription factor early growth response 1 (EGR-1)." (PMID 40395295, 2023).
pulmonary fibrosis (1 paper, 2023). Chronic progressive interstitial lung disorder characterized by the replacement of the lung tissue by connective tissue, leading to progressive dyspnea, respiratory failure, or right heart failure. "In addition, GABRA4 is abundantly expressed in human bronchial 16HBE cells and human pulmonary epithelial cells and is required to ameliorate pulmonary fibrosis." (PMID 40395295, 2023).
tuberculosis (1 paper, 2023). A chronic, recurrent infection caused by the bacterium Mycobacterium tuberculosis. "Because dysregulated inflammatory responses are associated with immune pathogenesis and tissue destruction in tuberculosis, we then tested to see whether Gabra4 deficiency is linked to altered regulation of inflammatory responses." (PMID 40395295, 2023).
infection (2 papers, 2021 to 2023). The state of being infected such as from the introduction of a foreign agent such as serum, vaccine, antigenic substance or organism. "Myeloid Gabra4 deficiency led to defective mycobacterial clearance during infection and increased susceptibility to septic shock." (PMID 40395295, 2023). "We found that myeloid deficiency of Gabra4 markedly suppressed mitochondrial respiration and decreased mtROS generation, which affected autophagy, during infection." (PMID 40395295, 2023). "Several peripheral innate immune cells are GABAergic, although there is little information on the function of immune cell-expressed GABRA4 in regulation of innate immunity during infection and inflammation." (PMID 40395295, 2023). "Future studies are warranted to clarify how GABRA4 expression and assembly are modulated in macrophages in the context of infection and inflammation." (PMID 40395295, 2023). "Our data show that the Ca2+-AMPK pathway is required for transcriptional activation of the essential autophagy genes Gabarap, Gabarapl1, Map1lc3a, and Foxo3 in the context of myeloid-specific Gabra4 signaling during infection." (PMID 40395295, 2023). "We evaluated the significance of GABRA4 signaling in host defense in macrophages during infection and inflammation." (PMID 40395295, 2023). "Gabra4 expression in myeloid cells is critical for activating autophagy and controlling excessive inflammatory responses during infection and inflammation." (PMID 40395295, 2023). "To investigate how GABRA4 is involved in autophagy during infection and inflammation, we performed qRT-PCR amplification of Gabarap and Gabarapl1, which are regulated by GABA-induced host defense in macrophages." (PMID 40395295, 2023). "We also addressed the role of GABRA4 in the elevation of mitochondrial respiration and ATP synthesis in macrophages during infection and inflammation." (PMID 40395295, 2023). "We further examined how GABRA4 signaling contributes to the regulation of pulmonary inflammation during infection." (PMID 40395295, 2023). "Together, these data implicate GABRA4 in the autophagy gene induction, autophagy activation and phagosomal maturation of Mtb in macrophages during infection." (PMID 40395295, 2023). "Herein, we identified myeloid GABAAR subunit α4 (Gabra4) as a critical regulator of autophagy and a promoter of host innate defense during infection and inflammation." (PMID 40395295, 2023). "Therefore, the HIF1A-LDHA pathway, regulated by GABRA4 signaling, is involved in activating autophagy and antimicrobial host defense during infection." (PMID 40395295, 2023). "Because autophagy is a quality-control system that regulates inflammatory responses to pathogens or danger signals, we assessed whether GABRA4-mediated AMPK activation controls inflammatory cytokine responses during infection." (PMID 40395295, 2023). "Given that in vivo bacterial load is higher in the Gabra4-deficient lung, we questioned whether alveolar macrophages (AMs) play a role in GABRA4-mediated host defense during infection." (PMID 40395295, 2023). "Moreover, GABRA4 is required to maintain mitochondrial respiration to generate mitochondrial reactive oxygen species (mtROS), which triggers autophagy and antimicrobial responses in the early phase of infection." (PMID 40395295, 2023). "Our data demonstrate that GABRA4 signaling, via AMPK pathway activation, orchestrates autophagy, antimicrobial host defense, inflammation, and immunometabolism in macrophages during infection and inflammation." (PMID 40395295, 2023). "Collectively, these data suggest involvement of the GABRA4-AMPK axis in the orchestration of autophagy, antimicrobial responses, and inflammatory responses in macrophages during infection." (PMID 40395295, 2023). "In contrast, infection of conditional shRNA AAV9 against Gabrb2 and Gabra4 attenuated the decline in body temperature of miR-33f/fDBH-Cre mice at a level equal to or greater than that of miR-33f/f mice." (PMID 33594062, 2021).
infection (continued). "Given that AMPK is a key mediator of energy metabolism and mitochondrial homeostasis, our data suggest that the GABRA4-AMPK axis orchestrates antimicrobial host defense by modulating autophagy, inflammation, and mitochondrial respiration during infection and inflammation." (PMID 40395295, 2023).
GABRA4 also shares sentences with these, for which no sentence is quoted: depression (5 papers); neurodevelopmental disorder (3); Intellectual disability (2); tumor (2); acne (1); alcoholism (1); amyotrophic lateral sclerosis (1); breast carcinoma (1); cancer (1); cognitive deficits (1); deafness (1); early infantile epileptic encephalopathy (1); glioma (1); juvenile amyotrophic lateral sclerosis (1); mood disorder (1); movement disorder (1); myocarditis (1); neurodegenerative disease (1); prostate carcinoma (1); psychiatric disorder (1); restless legs syndrome (1); substance abuse (1); Tremor (1); type 2 diabetes (1); viral myocarditis (1).